LINC02473 (long independently transcribed non-coding RNA 2473)
Gene: Long non-coding RNA gene on chromosome 4 (24,659,856 to 24,671,568, forward strand). Ensembl gene ENSG00000261121.
Diseases named in the same sentence as LINC02473 in open-access papers:
LINC02473 is named in the same sentence as 1 disease in open-access papers, as found by Europe PMC text mining. Sharing a sentence is not in itself a finding about the gene and the disease. The quoted sentences say what the papers report.
tumor (1 paper, 2020). "Almost all the genes in the ceRNA network have reported that they enrolled or associated with tumor progression, except for LINC02473, LINC0170, VPS9D1-AS1, C11orf44, and SCAT1." (PMID 32426332, 2020).